RNU6-667P (RNA, U6 small nuclear 667, pseudogene)
Gene: Small nuclear RNA gene on chromosome 15 (79,817,349 to 79,817,450, reverse strand). Ensembl gene ENSG00000252995.
Homologues: Orthologues: chimpanzee U6 (97% identical), macaque U6 (90% identical), guinea pig U6 (81% identical), pig U6 (72% identical). Paralogues in human: RNU6-1329P (83% identical), RNU6-379P (83% identical), RNU6-1123P (82% identical), RNU6-923P (82% identical), RNU6-944P (82% identical), RNU6-1094P (81% identical), RNU6-115P (81% identical), RNU6-1243P (81% identical), RNU6-797P (81% identical), RNU6-1029P (80% identical), RNU6-1089P (80% identical), RNU6-1159P (80% identical), and 1286 more.